TET2 (tet methylcytosine dioxygenase 2)
Diseases named in the same sentence as TET2 in open-access papers (continued):
Sharing a sentence is not in itself a finding about the gene and the disease.
myeloid malignancies (continued). "According to several in vivo and in vitro studies, mutated TET2 causes myeloid proliferation and development of myeloid malignancies, which further suggests that TET2 may act as a tumour suppressor in maintaining the homeostasis of hematopoietic cells." (PMID 36611455, 2023). "However, the frequency of biallelic TET2 mutations appears significantly higher in BPDCN compared to other myeloid malignancies." (PMID 36819168, 2023). "Additionally, Tet2 knockout has been associated with an increased risk of developing myeloid malignancies." (PMID 38131904, 2023). "These phenotypes are consistent with prevalence of myeloid disorders and malignancies linked to Tet2 loss in adult mice as well as with onset of more robust and aggressive myeloid malignancies associated with inducible combined deletion of Tet2 and Tet3 in adult mice." (PMID 35235365, 2022). "On the other hand, TET2 mutations have been widely identified various myeloid malignancies." (PMID 35309925, 2022). "For example, alterations in TET2 gene, one of the more commonly mutated genes in myeloid neoplasms, specifically co-occurred with NEB gene variations in control MPN patients, with the odds ratio for the co-occurrence being 11.6 times higher than that seen in MPN patients with SCs (p = 0.0138)." (PMID 35884495, 2022). "TET2 variants have also been associated with increased risk of myeloid malignancies." (PMID 35872888, 2022). "Similarly, in mouse models, germline deletion of the Tet1 or Tet2 genes is associated with B cell and myeloid malignancies respectively, and in each case develops with very long latency." (PMID 36266342, 2022). "In 2009, the TET2 gene was described in myeloid malignancies along with its variants." (PMID 34660059, 2021). "Moreover, the TET2 gene is frequently mutated in myeloid malignancies, and the depletion of Tet2 in mice led to myeloid transformation." (PMID 33946178, 2021). "However, whereas one third of TET2 knockout mice developed lethal myeloid malignancies within their first year of life, a causative relationship between TET2 deficiency and human malignancy is less clear." (PMID 33921666, 2021). "Interestingly, Tet2 haploinsufficiency contributes to transformation in vivo, consistent with the fact that Tet2 monoallelic loss is an important pathogenic event in myeloid malignancies." (PMID 33520997, 2020). "We examined the impacts of loss-of-function EZH2 mutations on the pathogenesis of myeloid malignancies using Ezh2 conditional knockout mice and demonstrated that an Ezh2 deficiency in combination with a Tet2 hypomorph in mice accelerates the transformation of HSCs and induces MDS and MDS/MPN." (PMID 33292805, 2020). "It is noted that TET2 mutations are consistently associated with a decrease in 5hmC, which has been suggested as a potential diagnostic and prognostic biomarker for hematopoietic malignancies, especially myeloid malignancies." (PMID 31001476, 2019). "TET2 plays a unique role also in hematopoietic stem cell differentiation and Tet2 mutations are associated with aberrant DNA methylation and myeloid malignancies." (PMID 29556496, 2018). "TET2 mutations were observed in 8 out of 19 patients (42 %) with myeloid neoplasms." (PMID 26984174, 2016). "TET2 mRNA expression levels, in addition to TET2 mutation status, may also play a role in myeloid neoplasm physiopathology." (PMID 26984174, 2016). "Functional studies manipulating TET2 have also been able to recapitulate phenotypes that are characteristic of myeloid neoplasms, suggesting that TET2 loss may be a key event in leukemic transformation." (PMID 24622842, 2014). "In addition to MDS, sAML, and MPNs, TET2 mutations have now been described in other myeloid neoplasms, such as de novo AML (12%) and chronic myelomonocytic leukemia (CMML; 42%–46%)." (PMID 24622842, 2014). "Furthermore, TET2 mutation status is significantly correlated with decreased global 5-hmC in myeloid tumors." (PMID 24622842, 2014).
myeloid malignancies (continued). "Our data confirm and extend those previously published and allow us to speculate that TET2 mutations could represent the biological link between different classes of myeloid malignancies." (PMID 23781511, 2013). "TET2 mutations were also reported in other myeloid malignancies." (PMID 23691452, 2012). "Therefore, selective TET inhibitors may offer a promising strategy for targeted treatment of TET2-associated myeloid neoplasms." (PMID 39626264, 2025). "However, TET2 deficiency promotes the formation of myeloid malignancies." (PMID 40599235, 2025). "Moreover, the TET2 mutant allele dosage has potential theranostic impact for myeloid neoplasms." (PMID 36819168, 2023). "Importantly, one third of Tet2 -/- and 8% of Tet2 +/- mice died within 1 year of age because of the development of myeloid malignancies reminiscent of CMML indicating that Tet2 loss may represent a predisposition for the development of this malignancy." (PMID 34660314, 2021). "In support of this possibility, mutations of IDH1 and IDH2 also occur in myeloid malignancies where neomorphic activity of the enzyme results in aberrant generation of 2-hydroxyglutarate, which inhibits the 2-oxoglutarate dependent conversion of 5mC to 5hmC by TET2." (PMID 25276435, 2014). "TET2 binding, a factor strongly linked to myeloid malignancies, was found to associate specifically with proliferation DMRs and ALL specific DMRs, suggesting a potential role for TET2 in ALL specific methylation changes." (PMID 41174288, 2026). "Systemic ascorbate depletion promotes the development of Tet2+/− or Tet2−/− myeloid neoplasms, suggesting TET2-dependent and TET2-independent effects." (PMID 40213851, 2025). "In the absence of these three major driver mutations, screening for other mutations associated with myeloid neoplasms, such as ASXL1, EZH2, TET2, IDH1, IDH2, SRSF2, and SF3B1, can help establish the clonal nature of the disease." (PMID 41514563, 2025). "Myeloid malignancies were diagnosed in 3 of 5 patients with ASXL1 variants, 1 of 4 with TET2 variants, and 0 of 3 patients with DNMT3A variants." (PMID 40179146, 2025). "NGS is essential for this diagnosis, as it enables detection of at least one somatic mutation in genes commonly mutated in myeloid neoplasms (e.g., DNMT3A, TET2, ASXL1, SF3B1, SRSF2, etc.)." (PMID 41464583, 2025). "ETNK1 mutation is an early event in myeloid neoplasms, often co-occurring with ASXL1, TET2, EZH2, RUNX1, and SRSF2 mutations." (PMID 40074445, 2025). "By modulating the numbers of Tet2-/- cells transplanted, recipient mice developed features of clonal hematopoiesis or myeloid malignancies." (PMID 39885602, 2025). "The interplay between DNMT3A and TET2 in myeloid neoplasms underscores a delicate balance in epigenetic regulation required for normal hematopoiesis." (PMID 40374809, 2025). "A series of publications in 2009 first reported acquired somatic TET2 mutations in myeloid disease, including myelodysplastic syndrome (MDS), myeloproliferative neoplasm (MPN), and myeloid malignancies." (PMID 40116537, 2025). "Hypomethylating agents like azacitidine and decitabine have shown increased efficacy in managing TET2-mutant myeloid malignancies, while high-dose vitamin C can limit the expansion of hematopoietic stem and progenitor cells (HSPCs) with TET2 deletions." (PMID 39997650, 2025). "Administration of ascorbate activates TET activity and suppresses aberrant HSC self-renewal and myeloid neoplasm in Tet2+/− mice." (PMID 38225226, 2024). "Certain m5C‐related genes, such as DNA methyltransferase 3 alpha (DNMT3A) and Tet methylcytosine dioxygenase 2 (TET2), frequently mutated in myeloid malignancies and are also associated with an increased risk of neurodegenerative disorders." (PMID 39691424, 2024).
myeloid malignancies (continued). "TET2 can mediate DNA 5mC oxidation and is an established tumour suppressor for myeloid malignancies." (PMID 39358506, 2024). "DMNT3A and TET2 mutations are frequently detected in CHIP and preleukemic phase of myeloid malignances." (PMID 38440231, 2024). "Epigenetic regulators DNMT3A, TET2, and ASXL1 are the three most frequently mutated genes in CH and are also linked to the initiation of myeloid malignancies, including AML." (PMID 38131904, 2023). "In myeloid malignancies, multiple alterations were noted in TET2 (n = 142, including 24/43 or 56% of AITL samples) and DNMT3A (n = 35), while in mantle cell lymphoma, ATM (n = 14, 10%) frequently harbored multiple mutations." (PMID 37898613, 2023). "miRNAs regulatory networks targeting TET2 mRNAs have been proposed as the primary post-transcriptionally regulatory mechanism during blood differentiation and in myeloid malignancies." (PMID 35159097, 2022). "An additional four CHIP genes (ASXL1, TET2, JAK2, and DDX41) were significantly associated with myeloid neoplasms and are likely driven by somatic alterations." (PMID 36199081, 2022). "Loss of TET2 function caused by the TET2 gene and IDH1/2 mutations is common in myeloid malignancies and lymphomas." (PMID 35223782, 2022). "The most common mutations in the epigenetic regulator genes are loss-of-function mutations in the Ten-Eleven Translocation 2 (TET2) gene, which were first identified in myeloid neoplasms." (PMID 35330161, 2022). "TET2 is the most frequently mutated gene in MDS (25–35%), and biallelic TET2 gene inactivation is frequently observed in myeloid neoplasms." (PMID 36030305, 2022). "This in vitro cell-line model was further confirmed in primary cells derived from patients with TET2 mutant myeloid neoplasms." (PMID 35085104, 2022). "Mutational profiling revealed mutations in four genes associated with myeloid malignancies, namely, EZH2, CUX1, TET2, and BCOR." (PMID 33628448, 2021). "Tet2 was first identified in myeloid malignancies and is considered to function as a DNA-modifying enzyme to oxidize 5mC to 5hmC." (PMID 34222235, 2021). "Of note, however, global Tet2-knockout mice show dysregulated hematopoietic stem cells, dysfunctional erythroid progenitors and development of myeloid malignancies, as well as abnormal development of immune cells." (PMID 35011643, 2021). "A share of TN MPNs discloses variants of myeloid neoplasm-/CHIP-associated genes (i.e., DNMT3A, TET2, and ASXL1) with ascertained or putative pathogenicity." (PMID 34830822, 2021). "The hypomethylating agents 5-azacytidine and decitabine show efficacy in myeloid neoplasms such as AML, and the response rate to these drugs appears to correlate with TET2, IDH1/2, and/or DNMT3A mutations." (PMID 33292562, 2020). "In particular, the combination of TET2 and SRSF2 mutations is very frequently observed in CMML and highly specific for myeloid neoplasm with monocytosis." (PMID 32674283, 2020). "While TET2 and DNMT3A mutations are two of most common genetic variations in CHIP and can precede myeloid malignancies, recent studies have also revealed associations between CHIP and other comorbid diseases." (PMID 31963585, 2020). "Alterations in Tet2 expression have been observed in myeloid malignancies, and TET2 has been shown to regulate myeloid and erythroid lineage differentiation." (PMID 32724310, 2020). "Next-generation sequencing (NGS) is used to detect and monitor clonal hematopoiesis, and the spectrum of mutations substantially overlaps with that of myeloid neoplasms with DNMT3A, TET2, ASXL1, and JAK2 being the most frequently mutated." (PMID 32825226, 2020). "Approximately 33% of homozygous TET2-mutant and 8% of heterozygous TET2-mutant mice developed lethal myeloid malignancies in the first year of life." (PMID 31001476, 2019).
myeloid malignancies (continued). "Each SF is also associated with a distinct pattern of mutations in other genes commonly detected in myeloid malignancies, as in the case of SRSF2 mutations with TET2 mutations in CMML and with RUNX1, IDH2, and ASXL1 mutations in AML." (PMID 31766606, 2019). "These were twice combined with additional mutations, including TET2 and SRSF2 mutations in a CMML case, and ASXL1, TET2, and U2AF1 mutations in the disseminated case of an undefined myeloid neoplasm accompanied by HLH (case 10)." (PMID 30084011, 2018). "We analyzed the mutation status of TET2 exons and the impact of this status on TET2 expression in bone marrow cells from myeloid neoplasm patients." (PMID 26984174, 2016). "TET2 is often silenced or mutated in myelo proliferative disease (MPD), myelodysplastic syndrome (MDS), chronic myelomonocytic leukemia (CMML) and lymphomas suggesting a tumor suppressor role for TET2 in myeloid tumors, MPD and MDS." (PMID 23938080, 2013). "Our dataset contained neutral polymorphisms and mutations associated with myeloid malignancies from epigenetic regulators ASXL1, DNMT3A, EZH2, and TET2." (PMID 24348198, 2013). "Inactivation of TET2 induces a decrease in the levels of 5 hmC in myeloid progenitors and a dysregulation of hematopoietic stem cells leading to the development of myeloid malignancies similar to CMML." (PMID 22328940, 2012). "TET2 protein has been shown to catalyze the conversion of 5 mC to 5 hmC, and patients with myeloid neoplasms have been demonstrated to display uniformly low levels of 5 hmC." (PMID 22328940, 2012). "Specifically, mutations at 12 residues in TET2 that co‐occur in solid tumors are reported in myeloid malignancies no < 4 times, with mutations at residues 544, 550, 1380, and 1516 being particularly recurrent in myeloid disease." (PMID 40116537, 2025). "Clonal hematopoiesis of indeterminate potential (CHIP) serves as a critical precursor to leukemogenesis, characterized by recurrent mutations—most frequently in DNMT3A, TET2, and ASXL1—that emerge in otherwise healthy individuals and significantly elevate the risk of AML and other myeloid neoplasms." (PMID 41451201, 2025). "TET2 deletion in murine hematopoietic stem cells (HSCs) altered early and late hematopoiesis in both myeloid and lymphoid lineages with eventual development of myeloid malignancies in the mice but only rarely mature lymphoid malignancies." (PMID 37841428, 2023). "Instances of germline variants in TET2 leading to familial malignancies are extremely rare, but such reports are available in patients with lymphomas and myeloid malignancies, but not particularly in MDS." (PMID 37884893, 2023). "Interestingly, a study assessing the catalytic dependent and independent requirements for Tet2 found that mice with catalytically inactive mutant mice developed myeloid malignancies reminiscent of MDS." (PMID 38028538, 2023). "TET2 and IDH2 mutations were mutually exclusive, a pattern consistent with other myeloid neoplasms." (PMID 36819168, 2023). "The gene encoding ten-eleven translocation 2 (tet2), a dioxygenase enzyme that catalyzes the conversion of 5-methylcytosine (5mC) to 5-hydroxymethylcytosine, is a recurrently mutated tumor suppressor gene in MDS and other myeloid malignancies." (PMID 37937078, 2023). "As TET2/DNMT3A‐mutated progenitor cells can differentiate into multilineage progenies and give rise to both AITL and myeloid neoplasms, they may also have the potential to lead to other metachronous/synchronous neoplasms." (PMID 35064935, 2022).
myeloid malignancies (continued). "Current evidence from animal models and clinical observations indicate that TET2 inactivation in hematopoietic stem cells may be an early event in the initiation of myeloid malignancies, and that additional hits are necessary for tumor progression." (PMID 35115654, 2022). "Moreover, they found mutations in known-CHIP-associated genes, including DNMT3A and TET2, in 22% of preleukemic RUNX1-FPD patients and 40% of patients with myeloid malignancy, which is more frequently than within the general population." (PMID 35884491, 2022). "TET2 and DNMT3A mutations are commonly found in clonal haematopoiesis and myeloid neoplasms." (PMID 35064935, 2022). "By this virtue, ascorbate could provide therapeutic opportunities able to overcome the TET2 impairment typical of myeloid neoplasms by re-establishing the net, residual TET-dioxygenase activity." (PMID 35938170, 2022). "Whole exome sequencing and next-generation sequencing in patients demonstrate cooccurrence of FLT3ITD, TET2, and DNMT3A mutations in patients with lymphoid and myeloid malignancies; however, it is unclear how these mutations cooperate and contribute to transformation and poor overall survival." (PMID 36073548, 2022). "TET2, which facilitates oxidation of methylcytosine in the DNA, thus contributing to the production of 5-hydroxymethylcytosine, is frequently deregulated in myeloid malignancies, and TET2 inactivation has been proposed to play an initiating role in age-related hematological cancers." (PMID 34885058, 2021). "TET2 mutations have been observed to co-occur with NPM1, FLT3-ITD, JAK2, ASXL1, calreticulin (CALR), SF3B1 and RUNX1 revealing the range of epigenetic connections to cellular processes amongst various myeloid malignancies." (PMID 34065087, 2021). "In this context, identifying mutations in MPN driver genes (JAK2, CALR, or MPL) or other myeloid neoplasm-associated genes (ASXL1, EZH2, TET2, IDH1, IDH2, SRSF2, and SF3B1) hints to the clonality of hematopoiesis and allows distinction from reactive conditions." (PMID 34830822, 2021). "TET2 mutations are frequent in myeloid malignancies and in elderly individuals with or without cytopenia." (PMID 34663818, 2021). "Understanding the impact of inactivating TET2 and DNMT3A mutations on myeloid cells is critical for elucidating the connection between CHIP, inflammation, and the pathogenesis of comorbid disease, as well as myeloid malignancies." (PMID 31963585, 2020). "Members of another family that were affected with a different heterozygous TET2 germline frameshift mutation all developed myeloid malignancy, possessed thyroid abnormalities, and had no history of cardiovascular disease." (PMID 31963585, 2020). "In addition to ARCH/CHIP, DNMT3A, TET2, and ASXL1 mutations are frequently detected in several myeloid malignancies, including MDS, MDS/MPN, and AML, suggesting that these mutations are the earliest events during malignant transformation." (PMID 33292805, 2020). "Recent studies provide hope for future therapeutic strategies that may address loss-of-function mutations in both the TET2 and DNMT3A genes in cases of myeloid malignancies, and potentially even CHIP and comorbid diseases." (PMID 31963585, 2020). "Since TET2 mutations occur frequently in other myeloid malignancies, these were unlikely to be disease-specific alterations." (PMID 31811114, 2019). "The presence of genetic abnormalities in genes related to the development of myeloid neoplasms in aging population (e.g., JAK2, DNMT3, TET2, and ASXL1) is associated with increased risk of hematologic malignancies, all-cause mortality, and cardiovascular disease." (PMID 30056580, 2018). "A large fraction of myeloid malignancies without TET2 (or other TET) mutations displayed low 5hmC levels, pointing to profound loss of TET enzymatic activity." (PMID 28408905, 2017). "The relevance of mutations in the TET2 promoter region has not been explored yet in myeloid neoplasms." (PMID 26984174, 2016).